EZH2 (enhancer of zeste 2 polycomb repressive complex 2 subunit)
Diseases named in the same sentence as EZH2 in open-access papers (continued):
Sharing a sentence is not in itself a finding about the gene and the disease.
tumor (continued). "EZH2 is a multifaceted oncogenic protein which facilitates tumor occurrence and proliferation mainly through methylation of tumor suppressor genes." (PMID 27880940, 2017). "More importantly, EZH2 has also been found to increase the proliferation of tumor cells and maintain the pluripotency of stem cells." (PMID 28415635, 2017). "EZH2 contributes to tumor development and progression, and represents an independent prognostic marker in patients with NPC24." (PMID 28360411, 2017). "EZH2 inhibition and reactivation of tumor suppressor microRNAs (miRNAs) represent attractive anti-cancer therapeutic strategies." (PMID 28088786, 2017). "For example, tanshindiols are small molecule inhibitors of EZH2 that also possess anti-cancer activity in several tumor cell lines." (PMID 28933369, 2017). "Curcumin was shown to inhibit of zeste homolog 2 (EZH2)-induced tumor cell proliferation, EMT, and metastasis in breast and lung cancers." (PMID 28587210, 2017). "We demonstrated that miR-361 is a tumor suppressor in EC, and EZH2 binds directly to the miR-361 promoter to suppress its transcription through a YY1-dependent manner." (PMID 28088786, 2017). "In tumors treated with 4 mM of NaVP, cells with a positive staining for the EZH2 protein were located mostly in the upper part of a tumor." (PMID 28642877, 2017). "MiR-98 is located in an intron of the HECT, UBA, and WWE domain-containing 1 gene on the short arm of the X chromosome, and acts as a tumor suppressor by targeting EZH2 and LIN28 in various cancers." (PMID 28587210, 2017). "We found significantly elevated expression of EZH2, Lucat1 and a lower expression of p57 in the tumor samples." (PMID 29371934, 2017). "Treatment of H460 tumor xenografts with GO-203/NPs32 resulted in marked downregulation of EZH2 (left and right), supporting the premise that targeting the MUC1-C cytoplasmic domain in vitro and in vivo is sufficient for suppression of EZH2 expression." (PMID 28785086, 2017). "The frequencies of cases showing high expression, which was defined as positive expression in>75% of tumor cells, were 55.2% (91/167) for EZH2, 32.3% (54/167) for SUZ12, 37.1% (62/167) for H3K27me3, and 31.1% (52/167) for BMI1." (PMID 28412742, 2017). "As far as brain cancers, EZH2 expression increases with tumor grade in adult and pediatric tumors and it is a poor prognostic factor." (PMID 28978137, 2017). "When signals activating Akt persist, the prolonged presence of Akt-insensitive Ezh2 in tumor-reactive CD8+ T cells is required for them to preserve their memory properties in vivo." (PMID 29242551, 2017). "In tumors treated with 8 mM of NaVP, only 6.3 ± 5% of all tumor cells were positively stained for the EZH2 protein." (PMID 28642877, 2017). "Together, our results identify a pathway, EZH2-miR-361-Twist, that positive regulates tumor malignancy by promoting cancer cell proliferation, invasion, and self-renewal, and further support EZH2 as a promising therapeutic anti-EC target." (PMID 28088786, 2017). "An inhibitor of EZH2 expression (DZNeP) has anti-tumor and anti-invasive activities against breast and other cancers." (PMID 28411283, 2017). "Transfer of Pmel-1 cells expressing Ezh2S21A had dramatically enhanced capacity to inhibit tumor growth compared to either Ezh2 or GFP control." (PMID 29242551, 2017). "Epigenetic regulators, including EZH2 and DNA methyltransferases, appear to have dual roles, acting as tumor suppressors or oncogenes in different malignancies, depending on the differentiation state of cells undergoing malignant change." (PMID 28179359, 2017). "EZH2 is expressed at higher levels in human IBC cell lines compared with normal human mammary epithelial cells, and the knockdown of EZH2 expression significantly suppressed cell growth and tumor spheroid formation of human IBC cells in vitro." (PMID 27926493, 2017).
tumor (continued). "Having demonstrated the profound effects of miR-524-5p and miR-324-5p on tumor suppression, we sought to examine the importance of EZH2 in miR-524-5p and miR-324-5p mediated cell proliferation." (PMID 29221202, 2017). "Here the authors show that Akt-mediated phosphorylation of the epigenetic regulator Ezh2 is critical for the generation of an anti-tumor CD8 T cell response and promotes the expansion of memory-precursors." (PMID 29242551, 2017). "We now provide new mechanistic insights on the anti-MM effects mediated by EZH2 inhibition via upregulation of tumor suppressor miRNAs and subsequent downregulation of MM-associated oncogenes." (PMID 28052011, 2017). "In high tumor Hp expression group, EZH2 (r = -0.53, p < 0.001), SALL4 (r = -0.4, p < 0.001), TCF3 (r = -0.45, p < 0.001) were also negatively correlated with Hp." (PMID 28158312, 2017). "Significant experimental evidence clearly demonstrates that EZH2 participates in a series of biological events in many cancer types, including tumor initiation, progression and metastasis." (PMID 28415635, 2017). "RNA silencing of EZH2 inhibited tumor growth in cell lines, induced apoptosis, and enhanced sensitivity to cisplatin." (PMID 27732970, 2017). "We previously showed that lncRNA PVT1 is significantly upregulated in LAD tissues and cells, and that it promotes cell proliferation through epigenetically repressing tumor suppressor LATS2 expression by interacting with EZH2." (PMID 28109288, 2017). "In MM, EZH2 expression is up-regulated and significantly correlative with tumor burden and other important variables that historically indicates poor prognosis." (PMID 27926488, 2017). "Accumulated studies indicated that inhibition of EZH2 by the small molecular inhibitors or gene knockdown results in reducing cancer cell growth and tumor formation." (PMID 28561778, 2017). "Our studies establish that chromatin state is a major determinant of the activation of the FA pathway and suggest an important role for the PRC2/EZH2 complex in the regulation of this critical tumor suppressor pathway." (PMID 29100324, 2017). "The chromatin remodeling enzyme EZH2 is probably the most attractive epigenetic modifier in cancers which has been shown to induce DR in tumor cells by silencing miRNAs and establishing a functional mutual interaction with miRNAs." (PMID 28623912, 2017). "EZH2 had been reported promoted tumor cell migration and invasion via epigenetic repression of E-cadherin." (PMID 29113337, 2017). "As the potent anti-tumor effect of GSK126 and other EZH2 inhibitors, preclinical and phase I/II clinical trials have been started evaluating several specific EZH2 inhibitors and promising anti-tumor activity have been obtained." (PMID 27926488, 2017). "EZH2 expression has been reported to be absent in normal BM plasma cells, whereas it was increased in MM cells and correlative with tumor burden during the disease progression, hinting a role of EZH2 during the tumorigenesis and progression of MM." (PMID 27926488, 2017). "This enabled us to observe the concomitant effects of WF and EZH2 on drug resistance of tumor cells." (PMID 28968986, 2017). "We identified tumor-suppressive let-7b and miR-361 as EZH2-downregulated miRNAs that attenuate EC cell proliferation, invasiveness, and cancer stem cell-like properties." (PMID 28088786, 2017). "As discussed in previous sections, EZH2 has a critical role in tumor initiation, growth and progression in urological cancers." (PMID 28410242, 2017). "Cell culture and animal models with EZH2 inhibitors show significantly decreased spheroid growths, cell cycle arrest, apoptosis, and tumor regression." (PMID 28265786, 2017). "EZH2 enhances immune evasion and tumor proliferation by repressing a defined gene expression program of immune receptor and apoptotic signaling." (PMID 28265786, 2017).
tumor (continued). "Within non-Hodgkin’s lymphoma tumors with EZH2 mutations, a combination of EPZ-6438 and traditional targeted chemotherapy prevented tumor growth." (PMID 29093822, 2017). "EZH2 was expressed heterogeneously throughout each tumour, and showed distinct colocalisation with both BRN2 and NFIB." (PMID 28119061, 2017). "Enhancer of zeste homolog 2 (EZH2) is the catalytic unit of polycomb repressive complex 2 (PRC2) which epigenetically silences many genes involved in tumor-suppressive mechanisms via the trimethylation of lysine 27 of histone H3 (H3K27me3)." (PMID 29228694, 2017). "The preferential target of DZNep is EZH2 as shown by the reduction in the level of this enzyme and H3K27me3 after treatment of tumor cells with this analog." (PMID 28261562, 2017). "The systematic review presented in this article identified ten studies evaluating survival from CRC related to the expression of EZH2 in tumour tissue, with OS as a measure of survival in eight of these works." (PMID 29061982, 2017). "miR-101a is downregulated in various types of cancer and functions as a tumor suppressor by repressing the polycomb group protein EZH2." (PMID 28558818, 2017). "The amount of EZH2 has been shown to be higher in colorectal cancer (CRC) tumor tissues comparing to that in paired normal tissue." (PMID 28561778, 2017). "Small molecule EZH2 inhibitors induce cell cycle arrest and apoptosis, and have demonstrated relevant anti-tumor activity in preclinical models of MM." (PMID 29290968, 2017). "Given that deregulated mRNA translation is a frequent feature of cancer and that eEF1A1 is highly expressed in many human tumours, these findings present new possibilities for the therapeutic targeting of EZH2 in AML." (PMID 28678185, 2017). "The effect of NEAT-1 on modulation of EZH2 expression further supports an effect of this lncRNA on tumor growth." (PMID 28122578, 2017). "We then used an integrative approach to search for potential tumor suppressor miRNAs regulated by EZH2." (PMID 28088786, 2017). "Our data provides strong evidence showing that these heterogeneous EZH2 expressing tumour populations are also BRN2 and NFIB positive and are likely mediated by BRN2 expression in an NFIB dependent manner." (PMID 28119061, 2017). "To investigate the role of CARLo-5 on EZH2-mediated Polycomb-dependent gene silencing, we found that miR-200b, as a target with tumor suppressor function of EZH2." (PMID 29050269, 2017). "Compared to normal tissue cells or benign tumor cells, EZH2 is overexpressed in and promotes tumor progression in various cancers." (PMID 28415635, 2017). "EZH2 overexpression manifests through histone hypermethylation, resulting in tumor proliferation, cell cycle dysregulation, metastatic spread, and angiogenesis." (PMID 29093822, 2017). "Although EZH2 play oncogenic roles in many cancer types, suppression of EZH2 promotes cancer progression in some cancer types, suggesting the tumor suppressive roles of EZH2." (PMID 28561778, 2017). "It was first reported that lncRNA HOTAIR silences the tumor suppressor genes by interacting with EZH2 and enhancing H3K27me3." (PMID 28854977, 2017). "We present for the first time a global expression profiling of miRNAs in response to EZH2 inhibition and propose EZH2 and H3K27me3 as regulators of tumor suppressor miRNAs in MM." (PMID 28052011, 2017). "Given its role as a transcriptional repressor, substantial efforts have been dedicated to understand the mechanism by which EZH2 drives tumor development." (PMID 28410242, 2017). "In the present study, we evaluated the anti-tumor activity of a specific EZH2 inhibitor GSK126, which counters the H3K27me3 increase in MM cells." (PMID 27926488, 2017). "Cross-talk with DNA methylation pathways is facilitated by the PRC2 complex, via the EZH2 histone methyltransferase, which directly recruits DNA methyltransferases and is required for DNA methylation of EZH2-target promoters in human tumour cell lines." (PMID 28587163, 2017).
tumor (continued). "Consistently, treatment of tumour cells with the commonly used EZH2 inhibitor dZNep, which leads to degradation of PRC2 core components, selectively induces Pja1 expression." (PMID 28067271, 2017). "Loss-of-function mutations in EZH2, EED, and SUZ12 have been reported for T-cell acute lymphoblastic leukemia (T-ALL) and MDS, suggesting a role as tumor suppressors in specific hematological malignancies." (PMID 28505071, 2017). "And in liver cancer, miR-101 represses tumor progression and sensitizes cancer cells to chemotherapeutic treatment through directly targeting EZH2." (PMID 29221202, 2017). "In this study, enhanced re-expression of genes with the dual modification, including several tumour suppressor genes, was obtained after combined treatments with an inhibitor of DNA methyltransferase and of EZH2." (PMID 28587163, 2017). "All these studies reported on the anti-MM effects of EZH2 inhibitors via reactivation of a set of PRC2 target genes with anti-tumor functions such as genes involved in apoptosis, cell differentiation, cell adhesion and migration." (PMID 28664185, 2017). "To verify the regulation of TIMP2 by EZH2, we performed loss- and gain-of-function experiments of EZH2 and examined TIMP2 expression, MMP2 and MMP9 expression and proteolytic activity, and tumor cell migration and invasion." (PMID 28620234, 2017). "Studies have also shown the role of EZH2 deregulation in tumor progression, metastasis and maintenance of CSC self-renewal properties." (PMID 28148257, 2017). "EZH2 promotes the epithelial to mesenchymal transition program which is a known mechanism inducing tumor aggressiveness and metastases." (PMID 28642877, 2017). "Except for the situation of EZH2 overexpression, co-culturing with WF induced significantly higher drug resistance in tumor cells." (PMID 28968986, 2017). "Taken together, these data indicate that EZH2 is specifically enriched in IM, both in primary tumors and in a residual tumor after systemic chemotherapy." (PMID 27842164, 2016). "Here, we confirmed that the Wnt/β-catenin pathway was stimulated by EZH2 in HeLa and SiHa cells, with activation of target genes, resulting in the promotion of cell growth and tumor formation." (PMID 27092879, 2016). "This targetable epigenetic factor, EZH2, is a histone methyltransferase that catalyzes formation of H3K27me3, which is known to silence tumor suppressor gene expression, thereby promoting tumorigenesis." (PMID 27842164, 2016). "Specific small molecules have been recently developed to exploit the oncogenic addiction of tumor cells to EZH2." (PMID 26497210, 2016). "In vivo xenograft experiments showed that EZH2 knockdown increased tumor volume by day 20 compared to injection with an shRNA control." (PMID 26812882, 2016). "We attempted to determine the in vivo relationship between GSK3β and phosphorylated EZH2 in human tumor samples by using antibodies against these phosphorylation sites, but the antibodies we generated did not work for immunohistochemical staining." (PMID 27494834, 2016). "E2F is involved in EZH2 deregulation in cancer and creates a double feedback between EZH2 and E2F-mediated cell proliferation and tumor progression." (PMID 27793053, 2016). "In conclusion, these divergent roles of EZH2 in human malignancies suggest context and tumor cell-type specificities." (PMID 27835578, 2016). "The loss of LNC00152 inhibited GC cell proliferation in vitro and suppressed tumor growth in vivo, likely by recruiting EZH2 to the p15 and p21 promoters and inhibiting their expression." (PMID 26799422, 2016). "It is possible that EZH2 facilitates this process during tumor metastasis, tilting the balance in favor of MET." (PMID 27563817, 2016).
tumor (continued). "Overexpression of EZH2 was found to correlate with tumor aggressiveness, metastasis, and poor prognosis in numerous cancers, including HCC." (PMID 26733151, 2016). "Two EZH2-mutant xenograft models in mice dosed orally with EPZ-6438 for 28 days remained tumor free for up to 63 days after stopping compound treatment." (PMID 27222667, 2016). "To further demonstrate that EZH2 knockdown reduces tumor-initiating capacity in vivo, we performed a functional in vivo assay by re-implanting cells from primary tumors into secondary nude mice." (PMID 27172794, 2016). "Previous studies in our laboratory and others demonstrated that EZH2 was involved in tumor progression through the regulation of cell growth, apoptosis and invasion." (PMID 27049834, 2016). "For example, in some studies, the percentage of positive-staining tumor cells larger than 10%, 25%, 30% or 50% were considered to be high EZH2 expression." (PMID 26683709, 2016). "EZH2 not only facilitate the proliferation, survival and transformation of cancer cells, but also impact the tumor immunity." (PMID 27784285, 2016). "Based on results above, we believed that Ezh2 not only involved in the carcinogenic process, but also activated in tumor progression." (PMID 27015363, 2016). "MiR-328 is a tumor suppressor miRNA and can be epigenetically targeted through EZH2 mediated histone modifications and DNA methylation." (PMID 27385092, 2016). "To further evaluate the effects of EZH2 on tumor growth in vivo, we established intracranial xenograft tumors in nude mice." (PMID 27385092, 2016). "Numerous studies suggest that DZNep induces death in tumor cells through EZH2 downregulation and H3K27me3 reduction." (PMID 27223261, 2016). "While some of the mutations are oncogenic (i.e., IDH1/2, EZH2, and DNMT3A), others are tumor suppressive (i.e., KDM6A, CREBBP/EP300, and SMARCB1)." (PMID 27999365, 2016). "A number of studies have shown that EZH2 overexpression plays a major role in the physiopathology of several hematological malignancies by promoting cell proliferation and inducing tumor cell phenotypes." (PMID 26497210, 2016). "Knockdown of EZH2 in liver cancer cell lines also reduces levels of the repressive H3K27me3 histone, resulting in re-expression of a distinct subpopulation of tumor suppressor miRNAs that control cell motility and adhesion." (PMID 27239288, 2016). "EZH2-mediated methylation plays a pivotal role in epigenetic silencing of tumor suppressor genes in cancer and is involved in fundamental cellular processes, such as cell fate decision, cell cycle regulation, senescence and cell differentiation." (PMID 26683709, 2016). "Univariate survival analysis revealed that, in addition to tumor differentiation, lymph node metastasis, and tumor stage, high EZH2 expression predicted poor prognosis (P < 0.05)." (PMID 26848980, 2016). "The significant association between EZH2 overexpression and HER2 also supports a role of EZH2 in regulation of tumor cell proliferation." (PMID 27113214, 2016). "EZH2 has a well known function in cellular proliferation through its modulation of H3K27me3 marks at promoters of tumour suppressors, e.g. CDKN2A genes, and alteration of pro-proliferative protein activity." (PMID 26964089, 2016). "Since EZH2 acts as a transcriptional repressor, inhibition of its activity restores genes expression including those of cell cycle inhibitors and tumor suppressors, leading to decreased cell proliferation." (PMID 26868841, 2016). "RNA interference mediated attenuation of EZH2 expression blunted the malignant phenotype in this setting, exerting inhibitory effects on cell proliferation, anchorage-independent growth, and tumor development in a xenograft mouse model." (PMID 27472460, 2016). "First, EZH2 overexpression was correlated with tumor cell aggressiveness, metastasis development and poor prognosis in different cancer types." (PMID 26497210, 2016).